STAT1 (signal transducer and activator of transcription 1)
Diseases named in the same sentence as STAT1 in open-access papers (continued):
Sharing a sentence is not in itself a finding about the gene and the disease.
epilepsy (4 papers, 2017 to 2025). A brain disorder characterized by episodes of abnormally increased neuronal discharge resulting in transient episodes of sensory or motor neurological dysfunction, or psychic dysfunction. "Functionally, the protein levels of STAT1 and dimerized STAT1 were increased in the hippocampi of Sh2d5-KO mice with epilepsy." (PMID 40857409, 2025). "To further confirm that STAT1 functionally participates in the regulation of epilepsy by SH2D5, we performed a rescue experiment in which STAT1 was inhibited with fludarabine." (PMID 40857409, 2025). "We identified and characterized the dynamics of a CSF1R-regulating GRN in epilepsy and validated STAT1 and STAT3 as main regulators of this GRN." (PMID 33819288, 2021). "In conclusion, our findings suggest that SH2D5 regulates autophagy in hippocampal neurons in the brain, thereby modulating the expression of STAT1 and subsequently influencing the transcription of NMDARs, ultimately affecting epilepsy-related behavioral phenotypes." (PMID 40857409, 2025). "Our findings suggest that STAT1 is the key gene regulated by SH2D5 in mice with epilepsy." (PMID 40857409, 2025). "KO of Sh2d5 increased STAT1 levels, inhibited NMDAR transcription, and alleviated epilepsy symptoms, while inhibiting STAT1 worsened seizures." (PMID 40857409, 2025). "VPA is generally used in the treatment of epilepsy, but recently, it has been found to be effective in the treatment of oncolytic herpes simplex virus (oHSV) infection, as this drug can inhibit the expression of IFN-β and the IFN-mediated proteins STAT1 and PKR in infected cells." (PMID 28486989, 2017).
gallbladder carcinoma (4 papers, 2019 to 2022). "High activity of the JAK/STAT1 pathway is also observed, among others, in gallbladder cancer cells." (PMID 34201791, 2021). "Hence, it was concluded that the downregulation of PTPRF (protein tyrosine phosphatase receptor type F), activation of STAT-1, and cell proliferation were noted in gallbladder carcinoma cells in comparison to the nonneoplastic cells." (PMID 35035811, 2022).
gastric tumor (4 papers, 2013 to 2025). "STAT1 and PD-L1 were upregulated in gastric tumor tissues compared with normal tissues and were associated with immune infiltration and poor prognosis based on the TCGA-STAD database." (PMID 35456965, 2022). "Myotubularin-related protein 2 (MTMR2) promotes gastric tumor progression by influencing the IFN-γ/STAT1 pathway." (PMID 40909948, 2025). "Although this study does not describe the specific effect of HOXC9 on the phosphorylation of STAT1, targeted inhibition of HOXC9 in gastric tumor cells may enhance the IFN-γ/STAT1 signaling, thereby overcoming tumor-induced resistance to IFN-γ-mediated apoptosis." (PMID 40909948, 2025). "A higher density of CD33+/p-STAT1+ cells was inversely related to infiltrating CD8+ T lymphocytes but not B cells, supporting that CD33+/p-STAT1+ cell might be a subset of MDSCs in gastric tumor tissue." (PMID 23307253, 2013).
gastroenteritis (4 papers, 2012 to 2022). An inflammatory disorder that affects the upper and lower gastrointestinal tract. "MNV-3 represents an attractive strain to study norovirus infections in vivo because it establishes persistence in wild-type mice, yet causes symptoms resembling gastroenteritis in immune-compromised STAT1−/− mice." (PMID 22495235, 2012). "We previously reported that MNV-3 is attenuated compared to MNV-1 in STAT1−/− mice which also have defective type I IFN signaling, causing self-limited gastroenteritis from which all animals quickly recover." (PMID 24039576, 2013). "Activation of this chemokine pathway further promotes an acute immune response and inflammation via the Stat proteins; Stat1 and Stat3 in case of the patients with retinitis and Stat4 in case of the patients with gastroenteritis which aggravates the severity of the disease." (PMID 35538132, 2022). "In addition, we show that these Nlrp3- and GSDMD-mediated responses do not contribute to the diarrheic manifestations of gastroenteritis but do promote MNV-induced intestinal inflammation and lethality in STAT1-deficient mice." (PMID 31017981, 2019).
glaucoma (4 papers, 2009 to 2023). Increased pressure in the eyeball due to obstruction of the outflow of aqueous humor. "Decreased IFN-γ and STAT1 signaling, therefore, contributes to the survival of activated ONHAs in glaucoma." (PMID 19426536, 2009). "To determine the signaling pathway involved in EPO-mediated phosphorylation of NRF2 in glaucoma, we assessed the ratio of phosphorylated to total PI3K, Akt, JNK, STAT1, STAT3, GSK3β, and MAPK." (PMID 36978804, 2023). "In a rat glaucoma model, but not after optic nerve transection, we found gene expression increases in STAT1 and STAT3." (PMID 32822415, 2020).
hemorrhagic fever (4 papers, 2011 to 2018). An infectious disease caused by certain viruses or bacteria that can damage the walls of tiny blood vessels, making them leak, and can hamper the blood's ability to clot and cause severe, life-threatening illness. "It is noteworthy that elevated levels of IL-6, IL-8, IL-10, G-CSF, and TNF-alpha, which were observed in MACV-infected STAT-1 knockout mice, are correlated with the severity of human Argentinean hemorrhagic fever, caused by the related Junín virus." (PMID 21672221, 2011). "CLEC5A/MDL-1, a member of the myeloid C-type lectin family expressed on macrophages and neutrophils, is critical for dengue virus (DV)-induced hemorrhagic fever and shock syndrome in Stat1−/− mice and ConA-treated wild type mice." (PMID 22536153, 2012). "Both the STAT1-/- and IFNAR-/- mice possess complete sets of murine immune systems, but their cells either have altered response to interferon signaling or do not respond to type I interferon signaling, respectively, leading to rapid disease more reminiscent of human hemorrhagic fever." (PMID 30011277, 2018).
Herpesviridae infection (4 papers, 2021 to 2024). "For example, humans with an autosomal dominant mutant form of human STAT1 (R274W) have heightened susceptibility to herpesvirus infections, and MHV68 infection of mice heterozygous for STAT1 R274W recapitulates this phenotype." (PMID 34586873, 2021). "Some reported mutations altering the susceptibility of herpes infections include those affecting Unc-93 homolog B1 (UNC)-93B, signal transducer and activator of transcription 1 (STAT1), and Toll-like receptor 3 (TLR3)." (PMID 33401749, 2021).
hypothyroidism (4 papers, 2016 to 2025). Abnormally low levels of thyroid hormone. "One possibility for STAT1 mutations causing hypothyroidism might be the formation of thyroid autoantibodies." (PMID 26604104, 2016). "However, the association between the STAT1 mutation p.A267V and hypothyroidism, which has been reported, was also seen in two of our families." (PMID 26604104, 2016). "Moreover, mutated STAT1 may contribute to hypothyroidism by interfering with thyrotropin signaling pathway." (PMID 26604104, 2016). "Only the most severely affected members with both CMC and thyroid disease harbored this STAT1 mutation, while other family members, solely suffering from hypothyroidism, did not carry it." (PMID 26604104, 2016).
intestinal infection (4 papers, 2019 to 2024). "In summary, our results suggest an important role of epithelial STAT1 during gastrointestinal infection by coordinating casaspase-8-dependent and -independent cell death pathways." (PMID 34497340, 2022). "In this study, we uncovered that epithelial STAT1 signaling orchestrates Caspase-8-dependent and -independent epithelial cell death during gastrointestinal infection." (PMID 34497340, 2022). "In summary, these data suggest that STAT1 has a key function in the intestinal epithelium by orchestrating cell death as a host response during intestinal infection with S. Typhimurium." (PMID 34497340, 2022). "Stat1-/- mice infected PO exhibited robust intestinal infection as well as viral dissemination to the spleen, consistent with the observation that type I IFN signaling limits extraintestinal spread of CR6, but dissemination to the brain was limited." (PMID 33705489, 2021). "Intestinal infection of Stat1-/- mice was similar between CR6 and CR6F514I, with increased levels of viral shedding in the stool and enhanced viral levels in ileum and colon compared to WT animals at 5 dpi, with no observable differences associated with F514I." (PMID 33705489, 2021). "Within this manuscript, we now demonstrate that in the context of gastrointestinal infection, STAT1 mediates epithelial cell death in the colon that might be an essential step to prevent infection, but is detrimental in genetically predisposed mice." (PMID 34497340, 2022). "On a molecular level, we uncovered that the transcription factor STAT1 induces gene expression of several key members of central cell death pathways and controls the activation of Caspase-8-dependent and -independent cell death in the intestinal epithelium during gastrointestinal infection." (PMID 34497340, 2022). "Having shown that STAT1 is involved in orchestrating Caspase-8-independent programmed necrosis during infection with the intracellular pathogen Salmonella, we were interested whether this is a widely used host defense mechanism during gastrointestinal infection." (PMID 34497340, 2022). "In summary, multiple pieces of evidence demonstrate that STAT1 and STAT3 both have essential functions during gastrointestinal infection by orchestrating epithelial barrier integrity." (PMID 34497340, 2022). "In summary, these data demonstrated that STAT1 acts upstream of Caspase-8-independent cell death in the colon during the initial phase of gastrointestinal infection, as lack of this transcription factor in Casp8ΔIEC mice was sufficient to block excessive cell death and lethality." (PMID 34497340, 2022). "Next, to determine whether the systemic spread of CR6 required initial intestinal infection for subsequent dissemination or could occur independent of the intestine, we analyzed the distribution of barcodes across tissues in WT, Ifnar1-/-, Ifnar1-/-Ifngr1-/-, and Stat1-/- mice." (PMID 38701091, 2024).
latent infection (4 papers, 2006 to 2024). "In contrast, we observed that B cell-specific STAT1 deficiency resulted in reduced latent infection of germinal center B cells and attenuated MHV68-driven germinal center response, unveiling a novel proviral role of B cell-intrinsic STAT1 expression during chronic gammaherpesvirus infection." (PMID 39440973, 2024). "Baricitinib can be a very effective treatment of mucosal inflammation in the early stages of CMC caused by STAT1 GOF mutations, before chronic pulmonary disease, and latent infections are established." (PMID 36050429, 2023). "Thus, in contrast to that observed for splenic B cells, B cell-intrinsic STAT1 expression attenuated latent infection of peritoneal B cells." (PMID 39440973, 2024). "In this study, we observed an increased frequency of latent infection, but not ex vivo reactivation, in peritoneal cells of mice with B cell-specific deficiency of either STAT1 or IFNAR1, implicating B cell-intrinsic type I IFN signaling in the control of the peritoneal latent reservoir." (PMID 39440973, 2024). "Viral manipulation of STAT1 to promote herpesvirus latency may be a common goal, as shown by the study from the Goodrum group demonstrating that HCMV-encoded UL138 promotes STAT1 activation to skew the balance between lytic and latent infection toward the latter." (PMID 39440973, 2024). "However, given the involvement of both STAT1 and IRF-3 in multiple signaling pathways, the role of T cell-intrinsic IFN signaling in supporting latent infection of germinal center B cells needs to be specifically defined." (PMID 35968944, 2022).
lymph node metastasis (4 papers, 2014 to 2022). "Therefore, we investigated if the good prognosis of male patients with prominent STAT1 expression in cancer cells is due to reduced vein invasion or lymph node metastasis." (PMID 29419930, 2018). "We then assessed if STAT1 expression detectable by IHC correlated with various and clinical and pathologic parameters, including gender, location and size of the tumor, lymph node metastasis, histologic grade, depth of tumor invasion and the overall clinical stage." (PMID 25355139, 2014).
metabolic syndrome (4 papers, 2009 to 2026). A cluster of metabolic risk factors for CARDIOVASCULAR DISEASES and TYPE 2 DIABETES MELLITUS. "In vitro, mimicking MASLD-associated dyslipidemia with palmitic acid, oleic acid, and cholesterol upregulated SAMHD1 expression, an IFN-γ-induced protein, accompanied by increased IFN-γ receptor 1 expression and STAT1 activation in HepG2 cells." (PMID 41522335, 2026).
metastatic tumors (4 papers, 2011 to 2025). "Lung tumor nodules were found by macroscopic observation, and the expression of STAT1 and phosphorylated-STAT1 was found to be upregulated in metastatic tumors in the lungs." (PMID 35313878, 2022). "TempO-Seq analysis showed upregulation of innate immune response and IRF pathway genes (IRF1, IRF7, IFNAR2, JAK1, STAT1), yet no reduction was observed in the metastatic tumors." (PMID 38516270, 2024).
nonalcoholic fatty liver disease (4 papers, 2021 to 2024). "Previous study showed that LECT2 expression is significantly elevated in nonalcoholic fatty liver disease, and LECT2 induces the development and progression of Nonalcoholic fatty liver disease through the STAT-1 signal pathway." (PMID 34899846, 2021). "In nonalcoholic fatty liver disease, OPN promoted macrophage M1 polarization by activation of the JAK1/STAT1/HMGB1 signaling pathway." (PMID 38250077, 2023).
pancreatic adenocarcinoma (4 papers, 2020 to 2025). "The pancreatic adenocarcinoma cell lines exhibited poor basal expression of STAT1, though they upregulated STAT1 following IFNβ treatment in wild type, but not IFNAR1ko cell lines." (PMID 32355214, 2020). "In contrast to malignancies such as pancreatic adenocarcinoma (PAAD) and low-grade glioma (LGG), elevated STAT1 expression in OV patients demonstrated significant association with survival advantage (HR = 0.74, p < 0.05), with the β isoform transcript exhibiting superior predictive efficacy." (PMID 40849492, 2025). "Pancreatic adenocarcinoma tumors exhibit increased levels of mRNA expression for components of the Transforming growth factor-β pathway (TGFB1/2/3, TGFBR1/2/3) and Interferon Type I pathways (IFNAR1, STAT1, IRF9 and IFI27)." (PMID 39457004, 2024).
Parkinson disease (4 papers, 2021 to 2025). A progressive degenerative disorder of the central nervous system characterized by loss of dopamine producing neurons in the substantia nigra and the presence of Lewy bodies in the substantia nigra and locus coeruleus. "Further, STAT1 is a potential target for Parkinson’s disease therapy; Apocynin, a herb derived from Picrorhiza kurroa, has been shown to alleviate learning and memory impairments in the mice model through suppression of STAT1 and NF-κB signaling pathways." (PMID 35214883, 2022). "Additionally, treatment with AZD1480 inhibited the activation of STAT1/3/4 and blocked the differentiation of Th1 and Th17 cells, jointly promoting an immune response in the Parkinson’s disease model." (PMID 39229261, 2024). "Therefore, spermidine's inhibition of NF‐κB and STAT1 signaling may suppress M1 polarization in microglia during Parkinson's disease." (PMID 40059454, 2025). "Spermidine pretreatment reduced M1 microglial polarization and promoted M2 microglial polarization by inhibiting the NF‐κB/STAT1 signaling pathways, thereby alleviating neuroinflammation in both the MPTP mouse model of Parkinson's disease and LPS‐stimulated BV2 cells." (PMID 40059454, 2025).
polyarticular JIA (4 papers, 2013 to 2021). "In the case of JIA, treatment-naive polyarticular JIA patients were found to have enhanced responsiveness to IFN-γ stimulation compared with controls (i.e., increased STAT1 and/or STAT3 phosphorylation in subsets of CD4 T cells and classical monocytes)." (PMID 33921679, 2021). "STAT1 is present in the oligoarticular JIA but not the RF-ve polyarticular JIA sub-cluster." (PMID 24886659, 2014).
progressive multifocal leukoencephalopathy (4 papers, 2018 to 2025). Progressive multifocal leukoencephalopathy (PML) is a neurological disorder that damages the myelin that covers and protects nerves in the white matter of the brain. "Gain of function mutations have been described for another important ISG inducer, STAT1, in patients with JC virus-induced progressive multifocal leukoencephalopathy (PML), including a novel L400Q mutation." (PMID 33498715, 2021). "More recently, progressive multifocal leukoencephalopathy (PML) caused by reactivation of JC virus was described in a small number of patients with STAT1 GOF, indicating a profound T cell deficiency in this condition." (PMID 30671054, 2018). "As one example of creative strategies based on measured differences in immune phenotype and function, there are case descriptions of STAT1 GOF patients developing progressive multifocal leukoencephalopathy (PML) associated with JC virus." (PMID 37670772, 2022). "Rituximab also has a black box warning for progressive multifocal leukoencephalopathy (PML), and this risk should be considered prior to use in patients with other risks such as IEI with increased risk of PML (e.g., STAT1 gain-of-function [GOF], DOCK8 deficiency, and severe CD4 lymphopenia)." (PMID 41608118, 2025).
schistosomiasis (4 papers, 2019 to 2025). An infectious disease caused by parasitic trematodes of the genus Schistosoma that colonize human blood vessels and release eggs that can cause granulomatous reactions leading to acute (swimmer's itch or acute schistosomiasis syndrome) or chronic disease. "For example, elevated miR-146a/b plays a protective role in schistosomiasis by inhibiting IFN-γ induced macrophage differentiation into M1 cells through targeting STAT1 during the development of Schistosomiasis japonica." (PMID 40895302, 2025).
steatosis (4 papers, 2022 to 2024). Increased lipid within the cytoplasm of cells. "However, hepatic TCPTP deficiency promoted STAT-1, 3, and 5 signaling, which facilitated steatosis in mice fed an HFD for 12 weeks, compared with control mice." (PMID 36670982, 2023). "Notably, hepatic TCPTP deficiency led to the accumulation of lipid droplets, a morphological feature of steatosis, and elevated the levels of liver SREBP1c and PPARγ, enabled by the activation of STAT-1 and STAT-3 signaling." (PMID 36670982, 2023). "Interestingly, in this study the authors found an uncoupling of steatosis and carcinogenesis; while STAT1 activation propagated liver steatosis, STAT3 mediated HCC development." (PMID 35269812, 2022). "The protective effect of this treatment, in which it promotes STAT1-dependent HSC inactivation, was observed in patients at different stages of MASLD, from mild/intense steatosis to steatohepatitis or fibrosis." (PMID 39062027, 2024). "Interestingly, the increase in STAT1 activation induced by RPV-based therapy was also evident in F0 patients, probably due to the presence of steatosis or steatohepatitis among these individuals." (PMID 39062027, 2024).